BRAF (B-Raf proto-oncogene, serine/threonine kinase)
Diseases named in the same sentence as BRAF in open-access papers (continued):
Sharing a sentence is not in itself a finding about the gene and the disease.
cancer (continued). "Of the three isoforms, BRAF is the most frequently mutated in cancer." (PMID 37892237, 2023). "Around 200 low-frequency cancer-associated mutations have been described in BRAF." (PMID 37892237, 2023). "Furthermore, KRAS and BRAF mutations correlate with GLUT1 overexpression by cancer cells and excessive dependence on aerobic glycolysis as an energy source." (PMID 36979659, 2023). "Dysregulation or mutation of BRAF is often the underlying cause of various types of cancer." (PMID 37163002, 2023). "All of these cancers were also positive for EU-TIRADS categorization or BRAF mutation." (PMID 37686562, 2023). "There are two types of serrated polyps from which BRAF-mutated cancers originate." (PMID 37620872, 2023). "Mutations in BRAF exon 15 lead to conformational changes in its activation loops, resulting in constitutively active BRAF proteins which are implicated in the development of several human cancer types." (PMID 36758042, 2023). "Interestingly, we showed that all cancers revealed during the rFNA of AUS-nuclear nodules were also positive for EU-TIRADS (category 5) or BRAF mutations." (PMID 37686562, 2023). "Canine BRAF V595E is orthologous to the BRAF V600E variant found in several human cancer subtypes, which leads to constitutive activation of the RAS/RAF/MAPK pathway and concomitant upregulation of critical cellular processes including cell growth, survival and proliferation." (PMID 37079639, 2023). "Similarly, patients with BRAF-mutant carcinomas with underlying HT had similar incidences of recurrence and non-recurrence (p = 0.57)." (PMID 37190300, 2023). "The identification of a metabolic vulnerability of BRAF-mutated carcinomas and the capacity BRAFi and diclofenac combination to target metabolism open new therapeutic perspectives in maximising drug efficacy and reducing the onset of secondary resistance and drug-related toxicity." (PMID 37198319, 2023). "In addition, the coexistence of TERT promoter mutations and BRAF V600E is thought to be a strong genetic background for promoting the aggressiveness of human cancers." (PMID 35903534, 2022). "Treatment of cancer cells with known drugs could shed further light on the underlying mechanisms for the association of NRas and BRAF in mutual clusters." (PMID 36304112, 2022). "Preclinical studies using established PTC cell lines support that RSPO4 overexpression is associated with BRAF V600E mutation and is a critical upstream event that promote activation of kinases of focal adhesion signaling known to drive cancer cell locomotion and invasion." (PMID 36611933, 2022). "Fusions (32 samples) were also observed in BRAF somatic mutations across all cancer types." (PMID 35910024, 2022). "Moreover, our results are consistent with studies performed by other research groups on different types of cancer caused by BRAF V600E mutation and suggests that BRAF V600E mutation can be a risk factor for liver tumor development." (PMID 35163468, 2022). "In contrast to other RAF homologues, BRAF is commonly mutated in cancers." (PMID 36079062, 2022). "Similarly, BRAF mutation was associated with the expression of CSC markers, and advanced cancer stage and metastasis, and BRAF inhibitors induce epithelial re-differentiation in human CRC cell lines." (PMID 35267511, 2022). "Many studies have shown that cancer cells carrying the BRAF V600E mutation can resist apoptosis, and the anti‐apoptosis effect caused by BRAF V600E may be a factor affecting drug resistance." (PMID 35748101, 2022). "BRAF is frequently mutated across multiple cancer types and in normal nevi." (PMID 35565240, 2022). "Next, the author asked if BRAF mutation classes are equally represented in different cancer types." (PMID 36275468, 2022).
cancer (continued). "The score was predictive of sensitivity to MEK and BRAF inhibitors across many cancer cell lines, and was significantly associated with progression-free survival (PFS) in retrospective analyses of patients treated with vemurafenib, a selective inhibitor of the mutated BRAF(V600E) kinase." (PMID 36358725, 2022). "The relative frequency of BRAF mutations also varies among different cancer subtypes." (PMID 36275468, 2022). "Since certain cancer genes (e.g. BRAF) share pathways with other more rarely mutated targets of driver alteration (e.g. ARAF, RAF1), it may be useful to consider mutational status in a set of genes as a predictive biomarker." (PMID 35803911, 2022). "BRAF is an oncogenic serine/threonine kinase which is frequently mutated in various cancers." (PMID 36079062, 2022). "In addition, patients with several BRAF-V600-mutated cancer types were treated with another BRAF inhibitor (vemurafenib) and achieved similar response rates, with 2 out of 9 BTC patients (22.0%) having partial responses." (PMID 36072793, 2022). "BRAF is a serine/threonine kinase that is commonly mutated across cancers." (PMID 35565240, 2022). "BRAFV600E represents the most common BRAF mutation in all human cancers." (PMID 36698391, 2022). "NAMPT over-expression is a feature of several cancers, not only the BRAF-mutated ones." (PMID 35272691, 2022). "N stage cancer patients are significantly less inclined to harbor BRAF, ROS1 and AKT1 mutations." (PMID 36429016, 2022). "Cancer cells with BRAF activation mutations are sensitive to small-molecule MEK inhibitors." (PMID 35899070, 2022). "Finally, the presence of the BRAF V600E mutation in genomic DNA extracted from 12 clinical biopsy samples from cancer patients was investigated in blind tests with our device." (PMID 35260588, 2022). "Genetic mutations of BRAF gene are more common and responsible for developing cardiovascular defects, retardation of mental growth, and also lead to the development of several cancers (A. Richards and Garg, 2010)." (PMID 36267655, 2022). "However, deregulation of this pathway is found in up to 30% of all human cancers and BRAF mutations can be identified in 1.5–3.5% of NSCLC patients." (PMID 36230797, 2022). "This association suggests that cucurbitacin D may have a role in targeting cancers with BRAF mutations or having an effect on BRAF." (PMID 35525914, 2022). "The BRAF V600E mutation is correlated with worse prognostic outcomes in several cancer types." (PMID 35186740, 2022). "Also, BRAF fusions that have been identified in different types of cancer at low frequencies promote dimerization and signal similar to BRAF with class 2 point mutations." (PMID 36275468, 2022). "Other alterations in known cancer genes included a BRAF hotspot V600E mutation in one OGC-MC." (PMID 35697931, 2022). "The BRAF V600E point mutation (c.1799T > A) leads to a substitution from valine to glutamic acid at position 600, and is the most common one in a subset of CNS tumors and other cancers." (PMID 35158978, 2022). "However, CTNNB1 and BRAF mutations are consistently overrepresented in AYAs across multiple cancer types." (PMID 36433963, 2022). "Further, BRAF overexpression and mutation is observed across cancers and targeting metabolic pathways, including CPT1a, may be an alternative approach to improving the response to treatment." (PMID 35565240, 2022). "Next, the frequencies of BRAF mutations across cancer types were determined." (PMID 36275468, 2022). "Next, the author investigated relative frequency of BRAF mutations in the different cancer types." (PMID 36275468, 2022). "In contrast, MSI high, BRAF mutated cancers have in general a better prognosis." (PMID 36079062, 2022).
cancer (continued). "BRAF-V600E (1799T>A) is one of the most frequently reported driver mutations in multiple types of cancers, and patients with such mutations could benefit from disrupting this mutant allele." (PMID 35468792, 2022). "The detection or testing for KRAS and BRAF gene mutation presents a blueprint and change to standard diagnostic guidelines for inpatient care and creates a major development in early decision-making in personalizing cancer care." (PMID 35782059, 2022). "Also, the distribution of BRAF mutations classes is highly unequal across cancer types and subtypes." (PMID 36275468, 2022). "This trial revealed that BRAF/MEK inhibition may be used as an efficient treatment option in the majority of BRAF V600-mutated cancers." (PMID 36358795, 2022). "The location distribution of BRAF mutations was dramatically different among numerous cancers." (PMID 35910024, 2022). "However, due to the large number of samples and the diverse cancer types included in the AACR Project GENIE dataset, the author was also able to report BRAF mutation frequencies for rarer cancer types and subtypes." (PMID 36275468, 2022). "In this study, we profiled the characteristics of BRAF in 32 TCGA cancer types by using the cBioPortal tool and the results showed that BRAF expression, methylation, mutations, locations, and CNVs dramatically differed among diverse cancer types, which had significant clinical implications." (PMID 35910024, 2022). "Interestingly, in early-stage cancers, NNMT mRNA expression is significantly higher in BRAF mutated than in BRAF wild type cancers." (PMID 35177765, 2022). "However, there is still controversy as to how different mutations of the same gene locus can change cancer prognosis, especially with regard to BRAF variants." (PMID 35080260, 2022). "The author could show that the frequency of BRAF mutations varies across cancer types and subtypes, and that the BRAF mutation classes are unequally distributed across cancer types and subtypes." (PMID 36275468, 2022). "Next, we investigated the effect of cancer-associated SPOP mutations on BRAF localization." (PMID 36585710, 2022). "Combinations with BRAF inhibitors in BRAF mutated cancers with ATM mutations or other homologous recombination defects could be a prime target." (PMID 36079062, 2022). "In addition, the V600E mutation is known to constitutively activate BRAF, and is the most prominent mutation in cancer." (PMID 35883461, 2022). "BRAF is a serine/threonine kinase frequently mutated in human cancers." (PMID 36500607, 2022). "Mutations in BRAF gene will lead to cancer development and progression." (PMID 35433454, 2022). "BRAF mutations are frequently found in cancer and considered oncogenic drivers." (PMID 36275468, 2022). "Moreover, some cancer-associated BRAF mutants (T121I and S122Y) evaded SPOP-mediated regulation and were stronger activators of the MAPK/ERK cascade than wild-type BRAF." (PMID 36585710, 2022). "Taken together, these results suggest that the role of AXIN2 may be different for each cancer, and BRAF mutations may affect AXIN2 expression." (PMID 35550582, 2022). "If we can inhibit the pathway of BRAF V600E regulating mPTP, it may have intervention and therapeutic effect on cancers with BRAF V600E mutations." (PMID 35748101, 2022). "The prevalence of high TMB, in the range associated with putative responses to immune checkpoint inhibitors, is also lower in metastatic BRAF mutated cancers, when evaluated from biopsy samples of metastatic sites compared with samples from biopsies of the primary tumor." (PMID 36079062, 2022). "In addition, the survival associations between BRAF expression and prognosis in distinct cancer types were conducted to explore its potential therapeutic implication." (PMID 35910024, 2022). "This suggests that BRAF mutations may contribute to the development of more advanced disease, such as cancer invasion." (PMID 36230541, 2022).
cancer (continued). "The overall somatic mutation frequency of BRAF was 7.7% for all cancer samples." (PMID 35910024, 2022). "Using permutation testing-based co-occurrence analyses, the author defined the genetic interactions of BRAF mutations in multiple cancer types and revealed unexplored genetic interactions that might define clinically relevant subgroups." (PMID 36275468, 2022). "Furthermore, the French National Cancer Institute (INCA) conducted a trial to assess the efficacy and safety of vemurafenib in cancers with various BRAF mutations." (PMID 35912223, 2022). "Interestingly, since mutations in the known cancer driver gene BRAF were found for the first time in a patient with liver cancer, we examined the effect of the mutations on hepatocytes." (PMID 35163468, 2022). "To highlight a possible association between NAMPT expression and BRAF mutations in human cancers, we analyzed the TCGA database showing that BRAF-mutated tumors (MUT, in red) display significantly higher levels of NAMPT, as reported by cumulative distribution function (P = 3.94 × 10–12)." (PMID 35272691, 2022). "This leads us to hypothesize that applying a dual inhibition, or even a triple inhibition, for Akt and/or ERK and Hsp90 simultaneously, may prove to be effective to sensitize carcinomas possessing BRAF mutations to Hsp90 inhibitors." (PMID 36012578, 2022). "Additionally, since BRAF mutation is thought to silence thyroid iodide-handling genes and make these carcinomas more resistant to radioiodine treatment, surgeons and endocrinologists should consider immediate management." (PMID 36555268, 2022). "The identified potentially lead compounds through the in-silico drug design might be able to reduce the BRAF mutated carcinoma." (PMID 36267655, 2022). "In addition, canine TCC harboring BRAF mutations will be a unique model for human cancers with BRAF signaling activation in the field of comparative oncology." (PMID 34502061, 2021). "BRAF mutations critically affect cancer growth and progression and are supposed to be a founder event for mutations occurring early in the initiation process of cancer." (PMID 33980169, 2021). "ARAF and CRAF mutations are far rarer in cancer and seem to behave like class 3 BRAF variants." (PMID 33367512, 2021). "KRAS- or BRAF-mutated cancer cells also exhibit oncogene addiction." (PMID 33793658, 2021). "Hence, although it is likely that BRAF-mutated cancer cells have a high baseline level of autophagic flux, it can be further elevated in response to pharmacological inhibition of BRAFV600E signaling." (PMID 34298710, 2021). "This pathway is altered in about 45% of all cancers, mainly due to mutations in BRAF and RAS." (PMID 34063682, 2021). "In contrary to APC, BRAF mutation is associated with high cancer immunity." (PMID 34211853, 2021). "BRAF is a serine-threonine MAPKKK involved in the RAS/RAF/MEK/ERK signalling pathway, which is implicated in a wide range of cellular functions including proliferation, differentiation, and apoptosis; mutations of the BRAF gene are very common in several types of cancer." (PMID 33803216, 2021). "These granulomatous disorders can occur in many conditions in cancer patients (i.e., related to opportunistic infections associated with cancer, systemic granulomatosis due to cancer treatment, especially checkpoint inhibitors or BRAF/MEK inhibitors)." (PMID 34359324, 2021). "The four cancer cell lines examined, harboring BRAF or NRAS mutations, were susceptible to LT." (PMID 34064422, 2021). "However, BRAF mutations must cooperate with other mechanisms for a fully cancerous state, as they are insufficient to induce cancer alone." (PMID 33980169, 2021). "In addition to cancers with BRAF mutations, TGF-β signaling is also associated with therapy resistance in cancers with hyperactive EGFR." (PMID 34917620, 2021). "However, BRAF-mutated cancers were more likely to be MSI, poorly differentiated, mucinous in histology and located in the proximal colon." (PMID 33809520, 2021).
cancer (continued). "In fact, these mutations could make the cancers more susceptible to immunotherapies as well as to anti-BRAF therapies." (PMID 33474634, 2021). "Moreover, the frequency of BRAF mutations reflected closely that reported in the Catalogue of Somatic Mutations in Cancer (COSMIC) database." (PMID 34104084, 2021). "Thus far, only two cases (L505H and L514V) have been reported to confer drug resistance as secondary mutations in BRAF(V600E)-driven cancers." (PMID 35582307, 2021). "Moreover, cancer cell proliferation and apoptosis, BRAF mutation, expression analyses of cell lines and tissues accounted for the main part of the basic research cluster." (PMID 34722236, 2021). "Therefore, vemurafenib, dabrafenib, and encorafenib constitute the first-line agents against advance cancers with BRAF(V600E) mutation in current clinical therapy, which significantly changes the landscape of cancer therapy." (PMID 35582307, 2021). "These genetic variants include a typical cancer driver mutations in BRAF." (PMID 33578810, 2021). "In clinical therapy, vemurafenib exhibited an exceptional efficacy with manageable side effects on cancers with BRAF(V600E) mutation as a single agent or combined with cobimetinib (MEK inhibitor), although drug resistance occurs after 6-8 months of administration." (PMID 35582307, 2021). "This was consistent with the findings from non-BRAF-mutated cancers." (PMID 34830178, 2021). "Mutation of BRAF reduces the ability of cancer cells to take up iodine." (PMID 35284335, 2021). "Therefore, based on the current pilot study, we would recommend considering BRAF V600E‐mutation analysis in all patients whose palpation‐guided FNAC is classified as Bethesda 1–4 unless cancer is proven otherwise." (PMID 34156770, 2021). "In addition to activating BRAF mutations, cancer-associated BRAF splicing variants caused by aberrant splicing have been reported." (PMID 33923658, 2021). "The data suggest that the mutational status of the cancer-driver BRAF gene might be crucial for the regulation of the expression of FRMD5 and its activity in PTC cells." (PMID 34201607, 2021). "Search terms included “signet ring cell”, “colorectal”, “colon”, “rectum”, “carcinoma”, “cancer”, “epidemiology”, “clinicopathological”, “molecular”, “genotype”, “mutation”, “microsatellite instability”, “BRAF”, “prognosis”, “survival”, “metastasis”, “surgery”, “chemotherapy”, and “treatment”." (PMID 34381313, 2021). "Clinically, trametinib has been approved for treating cancer patients with the BRAF V600E mutation." (PMID 33858332, 2021). "BRAF is a protein kinase that is frequently mutationally activated in cancer." (PMID 34298710, 2021). "These inhibitors have exhibited a promising efficacy towards most BRAF-mutated cancers." (PMID 32807225, 2020). "The level of BRAFV600E mRNA expression can to some extent be predictive of the subsequent expression of a mutant protein, and this may provide some insights to the role of BRAF mutations in cancer progression and prognosis." (PMID 32357861, 2020). "The average age of BRAF mutant cancers harboring APC mutation was 12 years less than APC wild-type." (PMID 32384699, 2020). "Indeed, the prevalence of BRAF-mutated CRC was relatively low (6.4%) in the Japanese Nationwide Cancer Genome Screening Project (SCRUM-Japan), compared to those of large-scale studies mainly conducted in Western countries (8–12%)." (PMID 33152998, 2020).